CGAS (cyclic GMP-AMP synthase)
Diseases named in the same sentence as CGAS in open-access papers (continued):
Sharing a sentence is not in itself a finding about the gene and the disease.
ZIKV infection (9 papers, 2019 to 2024). "Overall, the cGAS-STING signaling pathway in restricted ZIKV infection has been well summarized in several papers." (PMID 38693578, 2024). "It was reported that NLRP3 inflammasome activation, triggered by ZIKV infection in monocytes, promotes the cleavage of cGAS, resulting in the inhibition of initiating type I IFN signaling, and enhances viral replication." (PMID 35446851, 2022). "For example, Dengue virus NS2B protease cofactor targets the cGAS for lysosomal degradation, and ZIKV infection promotes the degradation of cGAS via activation of caspase-1." (PMID 34543359, 2021). "ZIKV infection might induce mitochondrial DNA release, activating DNA sensors such as DNA-PK or cGAS, which results in IFN-I and IFN-III transcription." (PMID 36311766, 2022). "ZIKV infection could also promote host mitochondrial DNA (mitoDNA) release (i.e., mitochondrial failure) that is sensed by cyclic GMP-AMP synthase (cGAS) and signals through the ER associated intermediate stimulator of IFN genes (STING)." (PMID 33810028, 2021). "Care was also taken in this report to examine the connection between the degradation of cGAS and the attenuation of IFN-I response observed during ZIKV infection using cGAS KO assays in both cell lines and PBMCs from healthy donors." (PMID 32899347, 2020). "With regards to ZIKV infection, a recent study found enhanced ZIKV replication and reduced IFN-β induction in cGAS–/– THP1 (human monocytic) cells and peripheral blood mononuclear cells." (PMID 31652496, 2019). "In summary, recent studies have demonstrated that TLRs, RLRs, and the cGAS-STING pathway play an important role in innate immune sensing and control of the ZIKV infection." (PMID 31652496, 2019). "For example, it has not been fully established whether cGAS senses mtDNA during ZIKV infection, or perhaps other host DNA species." (PMID 31652496, 2019).
esophageal squamous cell carcinoma (8 papers, 2021 to 2026). Esophageal squamous cell carcinoma (ESCC) is a type of esophageal carcinoma (EC) that can affect any part of the esophagus, but is usually located in the upper or middle third. "One study suggested that POLQ inhibition and FANCD2 deficiency activate cGAS-STING in esophageal squamous cell carcinoma." (PMID 36976649, 2023). "For example, Drp1 overexpression induces mitochondrial dysfunction, followed by cytoplasmic mtDNA stress and subsequent activation of the cGAS-STING pathway to promote esophageal squamous cell carcinoma progression." (PMID 39507763, 2024). "Their following recent work reported the activation of cGAS-STING signaling contributing to cytosolic mtDNA stress-induced autophagy in esophageal squamous cell carcinoma (ESCC)." (PMID 36154922, 2022). "For example, the activated cGAS-STING pathway promoted esophageal squamous cell carcinoma (ESCC) tumor growth by inducing autophagy." (PMID 40362284, 2025). "Our previous studies have demonstrated that abnormal mitochondrial dynamics and biogenesis induce cytosolic mtDNA stress and promote the proliferation of HCC and esophageal squamous cell carcinoma (ESCC) cells by activating the TLR9 and/or cGAS-STING pathway." (PMID 40038250, 2025).
Hyperglycemia (8 papers, 2023 to 2025). An increased concentration of glucose in the blood. "To summarize, the excessive activation of the cGAS-STING pathway is linked to hyperglycemia-induced chronic inflammation, metabolic abnormalities, and impaired angiogenesis, resulting in inflammation and compromised blood flow in the brain." (PMID 37915571, 2023). "Metabolic stressors in T2DM—hyperglycemia, lipotoxicity, and mitochondrial dysfunction—induce leakage of mitochondrial and microbial double-stranded DNA into the cytosol, where it engages cGAS and activates STING." (PMID 41020872, 2025). "In the diabetic milieu, chronic hyperglycemia and hyperlipidemia promote the release of mtDNA into the cytoplasm—a process further exacerbated by cell death—which activates the cGAS-STING pathway." (PMID 41020872, 2025). "Mechanistically, hyperglycaemia-induced oxidative stress promoted endothelial mitochondrial dysfunction and mtDNA release, which subsequently activated the cGAS-STING system and the cGAS-STING-dependent IRF3/NF-kB pathway, ultimately resulting in inflammation and apoptosis." (PMID 38129863, 2023). "Moreover, existing evidence has demonstrated that hyperglycemia has an impact on the production of vascular endothelial cells, potentially through the activation of the cGAS-STING pathway and the dysregulation of the Hippo-Yes-associated protein (YAP) pathway." (PMID 37915571, 2023). "Furthermore, we revealed that the hyperglycaemia-induced cytosolic translocation of mtDNA leads to cGAS-STING-dependent IRF3/NF-kB activation, resulting in inflammation and apoptosis." (PMID 38129863, 2023). "Finally, cGAS-STING signalling was activated by hyperglycaemia-induced mtDNA release, which promoted the expression of inflammatory cytokines through the IRF3/NF-kB pathway and ultimately resulted in diabetic aortic endothelial cell dysfunction." (PMID 38129863, 2023). "Brahma-related gene 1 (BRG1) drives AS progression by promoting dsDNA accumulation, activating the cGAS-STING pathway, and exacerbating hyperglycemia-induced myocardial inflammation and apoptosis." (PMID 40351606, 2025). "We found that BRG1 deficiency resulted in the accumulation of dsDNA and triggered cGAS-STING activation, exacerbating cardiomyocyte inflammation and apoptosis induced by hyperglycemia and hyperlipemia." (PMID 38867118, 2025). "In the placenta of gestational diabetes—also characterized by hyperglycemia—low PGC-1α and DsbA-L expression are thought to activate the cGAS-STING pathway." (PMID 41020872, 2025). "High expression of cGAS, STING, and TBK1 in adipocytes promotes IR and hyperglycemia." (PMID 40351606, 2025). "Hyperglycemia induces reactive oxygen species (ROS) overproduction, advanced glycation end products (AGEs) accumulation, and endoplasmic reticulum stress (ERS), which collectively activate key inflammatory pathways (NF-κB, NLRP3, cGAS-STING)." (PMID 41296389, 2025). "After 2 months of sustained hyperglycemia (serum glucose > 275 mg/dL), we found increased expression of both cGAS and STING in the retina of diabetic mice compared with nondiabetic mice." (PMID 37345657, 2023). "Given that hyperglycaemia-induced mitochondrial dysfunction can lead to mtDNA release and that the cGAS-STING system can be activated by cytosolic mtDNA, it is important to identify whether hyperglycaemia contributes to aortic endothelial cell injury through mtDNA-induced cGAS-STING activation." (PMID 38129863, 2023). "Additionally, hyperglycemia impairs mitochondrial integrity by suppressing the SIRT1/AMPK/PGC1α axis, triggering cardiomyocyte apoptosis and the release of mtDNA-containing extracellular vesicles, which can activate the cGAS-STING pathway upon uptake by adjacent fibroblasts." (PMID 41020872, 2025).
lung diseases (8 papers, 2020 to 2025). "The cGAS-STING pathway is implicated in a variety of pulmonary diseases." (PMID 41226461, 2025). "Many lung diseases are thought to be correlated with inflammation and autoimmune hyperactivation, and the cGAS–STING pathway has been introduced into the exploration of the mechanisms of these lung diseases because of its manifestation in diseases associated with inflammation." (PMID 34906241, 2021). "Recently, it has been shown that DNA release and cGAS-STING pathway activation can drive lung disease." (PMID 39908265, 2025). "Technologies like single-cell sequencing and spatial transcriptomics can also be employed to resolve the spatiotemporal heterogeneity of cGAS-STING signaling in various cell types at different stages of lung diseases." (PMID 41226461, 2025). "In this review, we summarize the role of the cGAS-STING signaling pathway in different lung diseases, highlighting its pivotal role in treatment." (PMID 41226461, 2025). "Recent studies have highlighted the involvement of aberrant activation of cGAS-STING contributes to fibrotic lung diseases." (PMID 37965345, 2023). "In most lung diseases characterized by increased inflammation and elevated levels of pro-inflammatory factors, inhibition of the cGAS-STING signaling provides an avenue for therapeutic intervention." (PMID 37965345, 2023). "This review systematically summarizes recent research advancements related to the cGAS-STING pathway in pulmonary diseases, with a specific focus on elucidating its multi-faceted roles and underlying molecular mechanisms across different respiratory conditions." (PMID 41226461, 2025). "Notably, the critical role of the cGAS-STING signaling pathway in various lung diseases offers new avenues for therapeutic research." (PMID 41226461, 2025). "Furthermore, the activation of the cGAS-STING pathway contributes to the inflammatory responses observed in pulmonary diseases." (PMID 41226461, 2025). "In addition, the cGAS-STING pathway was activated, and our data suggest that it may serve as a potential target in lung diseases associated with smoking." (PMID 39908265, 2025). "Further exploration is needed into the relationship between the cGAS-STING pathway and specific rare pulmonary diseases." (PMID 41226461, 2025). "In summary, research on the cGAS-STING pathway in pulmonary diseases still requires further refinement and exploration, and this pathway holds great potential for the treatment of pulmonary diseases." (PMID 41226461, 2025). "The cGAS-STING signaling pathway has been recognized as a critical mediator in the pathogenesis of various diseases, particularly in pulmonary disorders." (PMID 41226461, 2025). "The cyclic GMP-AMP synthase–stimulator of interferon genes (cGAS-STING) pathway, a central innate immune sensor of cytosolic DNA, plays a dual role in immunoregulation within pulmonary diseases." (PMID 41226461, 2025). "This review comprehensively summarizes the basic mechanism of the cGAS-STING pathway, its diverse roles across various pulmonary diseases, and the current landscape of potential therapeutic strategies targeting this pathway." (PMID 41226461, 2025). "The mechanistic underpinnings of the cGAS-STING pathway have been extensively characterized, with accumulating evidence elucidating its critical pathophysiological relevance in pulmonary disorders." (PMID 41226461, 2025). "Recently, researchers found that the release of self-DNA activated the cytosolic cGAS-STING pathway and led to inflammatory injury, participating in the pathogenesis of pulmonary diseases such as allergic asthma and COPD." (PMID 36982193, 2023). "In summary, DNA sensors, such as TLR9 and cGAS-STING, participate in the development of lifestyle-related diseases such as vascular, metabolic, kidney, and pulmonary diseases." (PMID 36176986, 2022).
malaria (8 papers, 2020 to 2025). Malaria is a serious and sometimes fatal disease caused by a parasite that commonly infects a certain type of mosquito which feeds on humans. "cGAS or STING deficiency in mice markedly prolongs mouse survival during lethal malaria Plasmodium yoelii nigeriensis N67C infections by reducing late interleukin (IL)‐6 production." (PMID 35635376, 2022). "Generally, cGAS-STING is a double edge sword for the host to fight against malaria, which strongly relies on parasite strains and host models." (PMID 36825026, 2023). "Here, cGAS‐STING signaling is identified to play a detrimental role in regulating anti‐malaria immunity." (PMID 35635376, 2022). "Here, this study reveals that cGAS‐STING signaling plays a detrimental role in regulating anti‐malaria immunity by cooperating with MyD88 to induce p38‐dependent late IL‐6 production and expanding CD11b+Ly6Chi proinflammatory monocytes." (PMID 35635376, 2022). "Other anti-malaria drugs, such as quinine, chloroquine, and hydroxychloroquine, inhibit cGAS activity by binding cGAS at R342 and K372 of the DNA binding site." (PMID 36139387, 2022). "Moreover, it has also been found that cGAS-deficient mice exhibit higher Plasmodium burdens during blood-stage malaria, suggesting an important role for cGAS in controlling parasitic infections." (PMID 40362284, 2025). "As for the mouse malaria model, we firstly reported activation of cGAS-STING, and MDA5-MAVS by P. y YM infection, triggered IRF3-mediated limited production of IFN-α/β, which then induced negative regulator SOCS1 inhibit RNA-TLR7-MyD88-dependent more puissant type I IFN responses." (PMID 36825026, 2023). "This suggested that a cGAS‐STING‐induced IL‐6 production at day four may play a key role in dampening the anti‐malaria immunity against lethal malaria N67C infections." (PMID 35635376, 2022). "Although many efforts have been paid for studies about the regulation of cGAS-STING, there are still lots of research gaps to be explored for the potential value of this signaling pathway in the prophylaxis and treatment of malaria." (PMID 36825026, 2023). "Overall, these researches indicate that cGAS is essential for Plasmodium gDNA detection and STING-triggered type I IFN responses during malaria." (PMID 36825026, 2023). "Given the importance of cGAS-STING and downstream signaling in anti-malaria immunity, emerging studies have focused on the regulation of this pathway." (PMID 36825026, 2023). "The cGAS/STING activation recruits myeloid differentiation factor 88 (MyD88) and specifically activates the p38-dependent signaling pathway to produce late IL-6, which expands CD11b+Ly6Chi proinflammatory monocytes to inhibit anti-malaria immunity." (PMID 36825026, 2023). "Moreover, SMPDL3A is a cyclic guanosine monophosphate–AMP degrading enzyme that restricts cGAS-STING signaling and may contribute to regulate type I interferon responses during malaria." (PMID 38271704, 2024). "Moreover, the blockage or ablation of the cGAS‐STING‐MyD88‐p38‐IL‐6 signaling axis or the depletion of CD11b+Ly6Chi proinflammatory monocytes provides mice a significant survival benefit during N67C and other lethal malaria‐strain infections." (PMID 35635376, 2022). "However, in some cases, cGAS-STING signaling enhances immunity in some non-lethal malaria models." (PMID 36825026, 2023).
osteoarthritis (8 papers, 2020 to 2026). A noninflammatory degenerative joint disease occurring chiefly in older persons, characterized by degeneration of the articular cartilage, hypertrophy of bone at the margins and changes in the synovial membrane. "More research is needed on the relationship between cGAS/STING pathway and senescence-associated human diseases such as neurodegenerative diseases, degenerative arthritis and cardiovascular diseases." (PMID 35006429, 2020). "This study not only elucidates the pathological function of MDVs in osteoarthritis progression but also expands our understanding of IPFP-MSC-derived EV mechanisms, particularly revealing a novel EV-mediated pathway for cGAS-STING activation." (PMID 41480405, 2026). "Future work could focus on the molecular mechanism of cGAS/STING pathway in senescence and aging-related diseases to see if GAS also has a regulatory effect such as neurodegenerative diseases, osteoarthritis, cardiovascular diseases, etc.." (PMID 35006429, 2020). "While endogenous DNA driven cGAS-STING activation is known, it is not clear whether exogenous DNA drives cGAS-STING in osteoarthritis." (PMID 41480405, 2026).
parasitic infections (8 papers, 2021 to 2025). "The importance of cGAS in the control of P. falciparum infection was confirmed in vivo, as cGAS-depleted mice showed a higher susceptibility to parasitic infection." (PMID 33708225, 2021). "Emerging evidence suggests that cGAS-STING cytosolic DNA sensing pathway contributes to pathogenesis of certain parasitic infections." (PMID 36405710, 2022). "In the context of microbial and parasitic infections, the definite regulatory mechanism and immune function of the cGAS-STING signal pathway remain unknown." (PMID 34956229, 2021). "Many reports have shown that the cGAS-STING signaling can be triggered by parasites including Plasmodium, Toxoplasma gondii, Leishmania, Trypanosoma, Schistosoma, while the role of the cGAS-STING pathway in parasite infections remains controversial." (PMID 37781354, 2023). "Similarly, in parasitic diseases or HIRI, cGAS-STING activation may enhance pathogen clearance or exacerbate tissue damage, depending on disease stage." (PMID 41438738, 2025). "Having established that cGAS-STING-TBK1 axis plays an important role in regulation of parasite burden in infected macrophages, we next asked whether a TBK1 inhibitor could be of benefit in inhibiting parasitemia in vitro and in vivo." (PMID 36405710, 2022).
tuberculosis (8 papers, 2019 to 2025). A chronic, recurrent infection caused by the bacterium Mycobacterium tuberculosis. "cGAS and M. tuberculosis are notably colocalized in the human tissue from patients with tuberculosis, and cGAS depleted mice are more susceptible to bacterial infection." (PMID 33708225, 2021). "There is strong evidence in tuberculosis and in cancer biology that potentiation of the cGAS-STING-IRF3 pathway leads to improved M.tb clearance and also improved antitumor responses in cancer." (PMID 38095464, 2024). "This study provides new insight into the interaction between cGAS and dendritic cells (DCs), which could be considered in the development of new drugs and vaccines against tuberculosis." (PMID 30791397, 2019). "Understanding how M. tuberculosis manipulates the cGAS-STING pathway provides valuable insights for developing novel TB vaccines and therapeutics." (PMID 40697819, 2025). "Of note, Parp9-deficient mice are susceptible to M. tuberculosis infection and exhibited increased TB pathology, elevated cGAS, 2′3′-cyclic GMP-AMP (cGAMP), and type I IFN expression, and upregulation of complement and coagulation pathways." (PMID 37200107, 2023). "By restricting phagosome rupture and export of bacterial material to the cell cytosol, low-cytokine inducing/severe TB M. tuberculosis isolates prevent the activation of the inflammasome, cGAS, RIG-I, and other intracellular signaling cascades as revealed by our global transcriptomic analysis." (PMID 32327653, 2020). "Despite the negative implication of cGAS-STING activation during tuberculosis, some studies suggest the importance of antimicrobial activities by cGAS, such as cytokine production, autophagy, and dendritic cell activation in protection against infection." (PMID 35626718, 2022). "Our research provides new insights into the cGAS pathway, DCs, and type I IFN, which could be considered to develop prevention or immunotherapy strategies against tuberculosis." (PMID 30791397, 2019). "Using M. tuberculosis infection of Parp9-deficient mice, we demonstrate that, unlike a virus-induced effect, there was an important negative regulatory role for Parp9 in DNA damage, cyclic GMP–AMP synthase (cGAS) expression, and type I IFN production during TB." (PMID 37200107, 2023).
ulcerative colitis (8 papers, 2022 to 2025). An inflammatory bowel disease involving the mucosal surface of the large intestine and rectum. "Based on the potential anti-inflammatory activity of GCV, this study aimed to investigate the therapeutic effects of ganciclovir on dextran sulfate sodium (DSS)-induced ulcerative colitis (UC), which may involve cyclic GMP-AMP synthase (cGAS)-stimulator of interferon genes (STING) pathways." (PMID 36467059, 2022). "Similarly, neutrophil extracellular traps (NETs) were found to trigger colonic barrier dysfunction through cGAS-STING pathway activation, further exacerbating ulcerative colitis." (PMID 41257293, 2025).